NEK6 (NIMA related kinase 6)
Description:
Protein kinase which plays an important role in mitotic cell cycle progression. Required for chromosome segregation at metaphase-anaphase transition, robust mitotic spindle formation and cytokinesis. Phosphorylates ATF4, CIRSR, PTN, RAD26L, RBBP6, RPS7, RPS6KB1, TRIP4, STAT3 and histones H1 and H3. Phosphorylates KIF11 to promote mitotic spindle formation. Involved in G2/M phase cell cycle arrest induced by DNA damage. Inhibition of activity results in apoptosis. Phosphorylates EML4 at 'Ser-144', promoting its dissociation from microtubules during mitosis which is required for efficient chromosome congression.
Synonyms: SID6-1512
Tractability: Small molecule: a high-quality ligand is known; it belongs to a druggable protein family. PROTAC: ubiquitination databases record sites on it; its protein half-life has been measured; a small molecule that binds it is known.
Target class: Other protein kinase NEK family; Kinase; Enzyme; Other protein kinase group; Protein Kinase
Gene: Protein-coding gene on chromosome 9 (124,257,606 to 124,353,307, forward strand). Ensembl gene ENSG00000119408.
Subcellular location: Cytoplasm; Nucleus; Nucleus speckle; Cytoplasm, cytoskeleton, microtubule organizing center, centrosome; Cytoplasm, cytoskeleton, spindle pole
Subcellular location (Human Protein Atlas): Cytosol; Nucleoplasm; Centriolar satellite
Pathways (Reactome):
Cell Cycle: Activation of NIMA Kinases NEK9, NEK6, NEK7; EML4 and NUDC in mitotic spindle formation; Nuclear Pore Complex (NPC) Disassembly
Gene Ontology:
Molecular function: ATP binding; DNA-binding transcription factor binding; kinesin binding; magnesium ion binding; protein binding; protein kinase binding; protein serine kinase activity; protein serine/threonine kinase activity; transcription corepressor binding; ubiquitin protein ligase binding; protein kinase activity
Biological process: chromosome segregation; peptidyl-serine phosphorylation; positive regulation of canonical NF-kappaB signal transduction; protein autophosphorylation; protein phosphorylation; regulation of mitotic metaphase/anaphase transition; mitotic nuclear membrane disassembly; mitotic spindle organization; regulation of cellular senescence; regulation of mitotic cell cycle; spindle assembly; regulation of chromosome organization
Cellular component: centriolar satellite; centrosome; cytoplasm; cytosol; nucleoplasm; nucleus; protein-containing complex; microtubule organizing center; nuclear speck; spindle pole
Genetic constraint (gnomAD): Loss-of-function variants: 21 observed, 31.25 expected, observed/expected ratio (o/e) 0.67, 90% interval 0.48 to 0.97. The upper end of that interval is the gene's LOEUF score, 0.97, which puts it in group 4 of 6, group 1 being the genes least tolerant of losing a copy. Missense variants: 278 observed, 380.8 expected, observed/expected ratio (o/e) 0.73, 90% interval 0.66 to 0.81. Synonymous variants: 154 observed, 151.63 expected, observed/expected ratio (o/e) 1.02, 90% interval 0.89 to 1.16.
Homologues: Orthologues: chimpanzee NEK6 (99% identical), macaque NEK6 (98% identical), dog NEK6 (97% identical), pig NEK6 (96% identical), guinea pig NEK6 (96% identical), mouse Nek6 (95% identical), rat Nek6 (93% identical), tropical clawed frog nek6 (86% identical), zebrafish nek6 (73% identical). Paralogues in human: NEK7 (76% identical), NEK9 (33% identical), NEK10 (33% identical), NEK3 (33% identical), NEK8 (32% identical), NEK5 (32% identical), NEK2 (31% identical), NEK11 (30% identical).
Diseases named in the same sentence as NEK6 in open-access papers:
NEK6 is named in the same sentence as 62 diseases in open-access papers, as found by Europe PMC text mining. Sharing a sentence is not in itself a finding about the gene and the disease. The quoted sentences say what the papers report.
breast carcinoma (15 papers, 2007 to 2025). "NEK6 is overexpressed in breast cancer, and its high expression is associated with histological grade, tumor size and TNM stage." (PMID 39895790, 2025). "For example, NEK2 has an important role in centrosome separation and is implicated in breast cancer progression, while NEK6, NEK7 and NEK9 are involved in mitotic spindle assembly, which requires regulation of microtubule polymerization." (PMID 36550548, 2022). "Previews researches showed in liver cancer, breast cancer and gastric cancer the high expression of NEK6 is associated with poor prognosis of patients." (PMID 35898455, 2022). "A recent study demonstrated overexpression of NEK6 transcripts in hepatocellular carcinoma, although it was found to be frequently expressed among 125 serine/threonine kinase genes implicated in breast cancer, colorectal cancer, lung cancer, and laryngeal cancer by in situ hybridisation." (PMID 18827816, 2008). "The expression level of NEK6 in breast cancer cells (MCF-7 and SK-BR-3) was higher than that in normal breast epithelial cells in MCF-10A, and the expression level of NEK8 and NEK11 was higher than that in normal epithelial cells in MCF-7 (p < 0.01)." (PMID 35368696, 2022). "Earlier studies have also demonstrated elevated expression of NEK6 in multiple malignancies, such as breast cancer, colorectal cancer, lung cancer, and laryngeal cancer." (PMID 35402517, 2022). "NIMA Related Kinase 6 (NEK6) encodes a kinase, which plays multiple roles in the tumor, including suppression of tumor cell senescence and facilitation of breast cancer cell proliferation." (PMID 36189312, 2022). "NEK6 is highly expressed in colorectal cancer, breast cancer, gastric cancer, prostate cancer, liver cancer, ovarian cancer, and thyroid cancer." (PMID 35898455, 2022). "DNA methylation expression levels concluded that cg17931972 from NEK2 and cg14289738 from NEK6 had the highest DNA methylation levels and significant prognostic value (likelihood ratio (LR) test p-value < 0.05) in breast cancer." (PMID 34834441, 2021). "In this study, the reduction of NEK6 expression was able to attenuate the proliferation and spheroid formation of breast cancer cells." (PMID 32294979, 2020). "The survival rates of patients with breast cancer were also evaluated in relation to NEK6 expression, and 69% of patients with high expression of NEK6 were shown to be alive versus 87% of those with low expression." (PMID 32294979, 2020). "NEK6 plays a role in promoting the proliferation of breast cancer cells and may become a promising therapeutic target for breast cancer." (PMID 39895790, 2025). "Previous studies have shown that NEK6 is significantly upregulated in breast cancer and may play a role in the proliferation of breast cancer cells." (PMID 35105934, 2022). "Moreover, NEK6 also plays a role as a tumor-suppressor gene in different cancers, including thyroid cancer, gastric cancer, hepatic cell cancer, and breast cancer." (PMID 34834441, 2021). "The mechanisms behind the roles of NEK6 in breast cancer still need to be elucidated." (PMID 32294979, 2020). "This then provides the first evidence tentatively linking Nek6 to carcinogenesis and, together with the fact that overexpression of catalytically-inactive Nek6 reduces the growth rate of MDA-MB-231 human breast cancer cells, highlights Nek6 as a potential chemotherapeutic target." (PMID 17727698, 2007). "The expression of NEK2, NEK6, and NEK11 were related to colorectal cancer, NEK2, NEK3, NEK5, NEK6, and NEK8 to breast cancer, and NEK2 and NEK6 to prostate cancer." (PMID 31906878, 2020). "Thus, NEK6 may participate in the uncontrolled proliferation and growth of breast cancer cells." (PMID 32294979, 2020). "Similar to NEK6, NEK7 is also involved in several types of cancer, such as hepatic cancer, squamous cell carcinoma of the head and neck and breast cancer." (PMID 32294979, 2020).
breast carcinoma (continued). "The mRNA level analysis of NEK genes in breast cancer cell lines and breast cancer patients from various data sources revealed that NEK2, NEK4, NEK5, NEK6, NEK8, and NEK11 are overexpressed in breast cancer and may be involved in breast cancer development." (PMID 37627077, 2023). "In all three cell lines tested, HEK293, the breast cancer cell line model MCF‐7, and U2‐OS cells, overexpression of the active NEK6 kinase reduced transcriptional activity in a dose‐dependent manner, an effect not observed with the kinase‐inactive NEK6 variant." (PMID 35225431, 2022). "Non-tumoral breast tissues showed low or absent expression of NEK6 whereas in breast cancer tissues NEK6 expression was highly detected in the nucleus and, to a lesser extent, in the cytoplasm." (PMID 32294979, 2020). "In addition, the expression of NEK6 was positively correlated with histological grade, tumor size, and TNM stage of breast cancer; therefore, we believe that NEK6 may be an important index for predicting the prognosis of patients with breast cancer." (PMID 35105934, 2022).
hepatocellular carcinoma (10 papers, 2008 to 2025). A malignant tumor that arises from hepatocytes. "Although another study has shown that miR-219-5p inhibits the progression of hepatocellular carcinoma by targeting NEK6, there are few reports on the miRNA regulation of NEK6 in COAD." (PMID 35096064, 2022). "In hepatocellular carcinoma, it was observed that Nek7 kinase activity increased in response to serum starvation, while Nek6 activity and expression was decreased; however, Nek6 expression was then quickly restored after serum addition." (PMID 35409400, 2022). "It was recently shown that NEK6 expression was significantly upregulated in hepatocellular carcinoma." (PMID 35402517, 2022). "Mutation in Nek1 and Nek8 genes are related to polycystic kidney disease, Nek6 overexpression is observed in hepatocellular carcinomas, and studies also show that Nek6 and Nek1 are related to DNA damage checkpoints." (PMID 25591119, 2015). "In hepatocellular carcinoma, NEK6 is highly expressed and promotes cell proliferation." (PMID 39895790, 2025). "The NEK6 transcript has been reported to be significantly upregulated in hepatocellular carcinoma." (PMID 35402517, 2022). "NEK6 was elevated in about 70% of hepatocellular carcinoma (HCC) cases and the expression of NEK6 was elevated in correlation with the progression of HCC tissue grade." (PMID 41560755, 2025). "Increasing evidence suggests the involvement of NEK6 in the progression of hepatocellular carcinoma (HCC)." (PMID 32294979, 2020). "The aim of this study was to investigate the potential roles and internal mechanism of Nek6 in hepatocellular carcinoma (HCC) development." (PMID 25120679, 2014). "NEK6, with kinase activity, has been reported to block SMAD4 nuclear translocation and prevent growth arrest in hepatocellular carcinoma cells." (PMID 39256367, 2024). "The current study revealed that both miR-323a-3p and NEK6 could regulate the cell phenotype by targeting the TGF-β signaling pathway in some diseases, including hepatocellular carcinoma, pancreatic ductal adenocarcinoma, lung fibrosis, and cardiac fibrosis." (PMID 35096064, 2022).
gastric cancer (7 papers, 2008 to 2024). A primary or metastatic malignant neoplasm involving the stomach. "Another study associated NEK6 up-regulation in gastric cancer with distant and lymph node metastasis." (PMID 32294979, 2020). "Nek2, which belongs to the same family as Nek6, has been reported to inhibit autophagy in gastric cancer via activating AKT signaling pathway." (PMID 39702325, 2024). "Nek2, a member of the same family as Nek6, was reported to inhibit autophagy in gastric cancer via activating protein kinase B (Akt)/mammalian target of rapamycin (mTOR) signaling pathway." (PMID 39702325, 2024). "Some studies have also shown that NEK6 is overexpressed in advanced gastric cancer and in 70% of liver cancer patients." (PMID 35105934, 2022). "As stated, this study identified several genes, such as LUM and NEK6, which were not previously associated with human gastric cancer." (PMID 18827816, 2008). "In this study, the results of the bioinformatic analysis showed that among NEKs, the expressions of NEK2, NEK6, and NEK7 are upregulated, whereas NEK3 and NEK7 are related to the poor prognosis of gastric cancer." (PMID 34419048, 2021). "Western blotting showed strong bands for both NEK6 and INHBA in gastric cancer tissues compared to normal tissue in all three pairs." (PMID 18827816, 2008). "Three of these are known to be involved in gastric cancer: MMP7, SPARC, and SOD2, and the other four have no such reported associations (INHBA, IGFBP7, NEK6, and LUM)." (PMID 18827816, 2008). "However, no previous studies have shown NEK6 expression in gastric cancers or NEK6 protein expression in any cancerous tissues." (PMID 18827816, 2008). "In particular, NEK6 and INHBA are promising potential markers of gastric cancer regardless of disease stage." (PMID 18827816, 2008).
prostate carcinoma (7 papers, 2020 to 2026). A carcinoma that arises from epithelial cells of the prostate gland. "Consistently, overexpression of NEK6 has also been linked to the etiology and progression of several cancers, including osteosarcoma, breast cancer, prostate cancer, hepatocellular carcinoma, colon cancer, gastric cancer, and ovarian cancer." (PMID 41154634, 2025). "We recently generated, by CRISPR-Cas9 technology, a DU-145 prostate cancer cell line, with an NEK6 gene knockout." (PMID 42193938, 2026). "In prostate cancer, NEK6 affects redox balance and DDR, influencing the sensitivity of cancer cells to chemotherapeutic agents like cisplatin." (PMID 41154634, 2025). "The NEK6 lack in DU-145 prostate cancer cells reduced the proliferation, viability, and mitochondrial membrane potential and induced apoptosis." (PMID 36672191, 2023). "This study showed that NEK6 regulates the redox balance and DNA damage response in a model of a castration-resistant prostate cancer cell line." (PMID 36672191, 2023). "We believe that the role of NEK6 in other prostate cancer cell lines should be further investigated, but our present data point out an important role of NEK6 in cisplatin sensitivity and as a co-adjuvant therapy for prostate cancer treatment." (PMID 36672191, 2023). "Considering the cellular effects of a NEK6 lack on DNA damage and apoptosis, we suggest that future studies can explore NEK6 inhibitors as potential inducers of synthetic lethality in prostate cancer." (PMID 36672191, 2023). "A relevant study showed that the NEK6 signaling pathway is the main mechanism responsible for castration resistance in prostate cancer (CRPC)." (PMID 32294979, 2020). "NEK6 has been reported to be a central kinase responsible for the development of castrated tolerant prostate cancer 5, and knocking out NEK6 can reduce clonogenesis, proliferation, cell viability and mitochondrial activity and further increase intracellular reactive oxygen species (ROS) levels." (PMID 39895790, 2025). "A high-throughput genetic screen designed to establish new kinases involved in CRPC identified the NEK6 protein as a central kinase that mediates androgen-independent tumor growth and determined that NEK6 is aberrantly expressed in human prostate cancer and several prostate cancer cell lines." (PMID 36672191, 2023). "Thus, understanding the mechanisms that NEK6 regulates in prostate cancer models becomes essential for the design of NEK6 inhibitors." (PMID 36672191, 2023). "Moreover, NEK6 could participate in the development of castration resistance in prostate cancer." (PMID 36189312, 2022). "The study suggested that NEK6 may be related to cell survival pathways since no significant changes in proliferation or cell cycle progression were observed in NEK6 overexpressing prostate cancer cells." (PMID 32294979, 2020).
colorectal cancer (6 papers, 2008 to 2026). A primary or metastatic malignant neoplasm that affects the colon or rectum. "NEK6 overexpression also exists in colorectal cancer (CRC) and colorectal adenomatous polyp (CRAP) and was significantly correlated with the large polyp diameter." (PMID 35096064, 2022).
ovarian carcinoma (6 papers, 2020 to 2025). A malignant neoplasm originating from the surface ovarian epithelium. "In ovarian cancer, NEK6 overexpression is associated with adverse outcomes and drug resistance, possibly through its cooperation with HIF-1α." (PMID 41154634, 2025). "In our study, NEK6 was associated with chemoresistance and poor prognosis in ovarian cancer." (PMID 39256367, 2024). "Gao found NEK6 was highly expressed in ovarian cancer (OC) and NEK6 knockdown led to inhibited growth, migration and invasion while promoting the apoptosis of OC cells." (PMID 41560755, 2025). "Here, we found that PAE, a bioactive phenol, possesses NEK6 inhibitory activity and can inhibit de novo purine synthesis and chemoresistance in ovarian cancer." (PMID 39256367, 2024). "Analyzing protein IHC data from the HPA database, we observed elevated expression of PKD1 and NEK6 proteins in ovarian cancer compared to normal ovarian tissue." (PMID 39256367, 2024). "In vivo, NEK6 knockdown significantly enhances sensitivity to DOX in ovarian cancer xenografts derived from SKOV3/DDP cells and reduces tumor volume." (PMID 39256367, 2024). "The overactivation of de novo purine synthesis is evident in chemoresistant ovarian cancer, with NEK6 identified as a key molecule." (PMID 39256367, 2024). "The NEK6-mediated reprogramming of de novo purine synthesis emerges as a critical pathway influencing chemoresistance in ovarian cancer." (PMID 39256367, 2024). "Inhibiting NEK6 led to decreased de novo purine synthesis, resulting in diminished chemoresistance in ovarian cancer cells." (PMID 39256367, 2024). "Subsequently, we found that NEK6 knockdown inhibited FOXO3 S7 phosphorylation in chemoresistant ovarian cancer cells." (PMID 39256367, 2024). "We previously examined the expression of NEK6 in ovarian cancer tissues." (PMID 39256367, 2024). "Chemoresistant ovarian cancers exhibited higher purine abundance and NEK6 expression." (PMID 39256367, 2024). "Integrating these observations, we posit that NEK6 may serve as a pivotal nexus linking chemoresistance and de novo purine synthesis in ovarian cancer." (PMID 39256367, 2024). "Notably, chemoresistant ovarian cancer tissues exhibited significantly elevated NEK6 protein levels compared to their chemosensitive counterparts." (PMID 39256367, 2024). "This speculation gained further support as we validated higher NEK6 expression in chemoresistant ovarian cancer cells within in vitro cell line models." (PMID 39256367, 2024). "Furthermore, purine supplementation reduced apoptosis induced by DOX in NEK6-knockdown ovarian cancer xenografts." (PMID 39256367, 2024). "Additionally, we identified paeonol (PAE) as a promising agent for inhibiting NEK6-mediated chemoresistance in ovarian cancer." (PMID 39256367, 2024). "In conclusion, our data suggest that NEK6 may promote chemotherapy resistance and DNA damage repair in ovarian cancer by activating de novo purine synthesis." (PMID 39256367, 2024). "Evidence suggests that NEK6 is a downstream target of HIF-1α in ovarian cancer." (PMID 32294979, 2020). "Consequently, targeting the NEK6/HIF-1α axis may represent a novel therapeutic strategy to improve treatment outcomes in patients with treatment-resistant ovarian cancer." (PMID 41154634, 2025). "The results showed that NEK6 was able to exert a direct interaction with FOXO3 in both chemosensitive and chemoresistant ovarian cancer cells." (PMID 39256367, 2024).